INS (insulin)
Diseases named in the same sentence as INS in open-access papers (continued):
Sharing a sentence is not in itself a finding about the gene and the disease.
Insulin resistance (continued). "Since hepatic insulin resistance can impair glucagon signaling and gluconeogenesis, restoring hepatic insulin sensitivity may have indirect benefits for glucose counterregulation." (PMID 38298268, 2023). "Insulin resistance with compensatory increase in insulin production precedes human type 2 DM." (PMID 37730757, 2023). "However, hyperinsulinemia, insulin resistance, and reduced insulin sensitivity previously observed at 10 weeks in mice fed the high-fat/sucrose diet persisted at 20 weeks." (PMID 36674448, 2023). "Recent evidence supports a model in which prevention of hypersecretion of insulin and hyperinsulinemia may be critical for alleviation of insulin resistance and protecting β cell functionality and survival." (PMID 37279064, 2023). "Since age‐impaired glucose homeostasis is associated with insulin resistance and defects in insulin signaling in skeletal muscle, we investigated the effect of reversine treatment on insulin sensitivity, by measuring ECAR after treating the cells with insulin." (PMID 36625257, 2023). "Indeed, an inverse relationship between whole-body insulin resistance markers (HbA1c, fasting insulin, and HOMA-IR) and REM sleep was observed in our study." (PMID 39434962, 2023). "Since NAFLD is closely connected with the insulin resistance, there comes an increased need for insulin that may have a potential for weight gain." (PMID 38223606, 2023). "Finally, the HOMA2 model is a structural computer model of the glucose–insulin feedback system in the homeostatic state and is used to measure insulin resistance." (PMID 37111205, 2023). "Insulin mediates the glucose intake of the liver, and insulin resistance can lead to hepatic lipid accumulation and abnormal glucose regulation, which may eventually result in liver fibrosis." (PMID 37817864, 2023). "Most clinical data on insulin signaling in thyroid cancer derive from the hypothesis that insulin-resistance, typical of obesity, metabolic syndrome and T2DM, could be a risk factor for thyroid cancer development." (PMID 38146457, 2023). "As Akt2 is essential in insulin resistance, we further tested whether the inhibition of Akt2 signaling could suppress insulin‐dependent glucose uptake." (PMID 36625257, 2023). "When comparing the changes from baseline to 9 weeks of consumption of the two yogurts, the elevation in insulin resistance was milder in the probiotic group compared with the conventional group, as suggested by the lower elevation in serum insulin levels and decrease in HOMA-IR index." (PMID 37049473, 2023). "To this end, we isolated hepatocytes from C57BL/6 mice that were fed either a standard chow-diet, a HFD to promote obesity, insulin resistance, and steatosis, or a choline-deficient HFD (CD-HFD) to promote obesity, insulin resistance, and progression to NASH and fibrosis." (PMID 38060313, 2023). "Thus, resistin both induces insulin resistance and impairs insulin secretion in pancreatic beta cells, as well as tumor necrosis factor α (TNF-α) and fetuin-A." (PMID 37373556, 2023). "According to the “fetal insulin hypothesis” genetically determined insulin resistance results in an impaired insulin-mediated growth in the fetus and in the development of insulin resistance in adulthood." (PMID 37342257, 2023). "Fe is one of the most potent oxidants to induce insulin resistance and interfere with insulin release from pancreatic β cells and is involved in the pathogenesis of GDM; Zn promotes the development of GDM by interfering with insulin metabolism and glucose homeostasis." (PMID 36418636, 2023). "Insensitivity of target organs to insulin following insulin resistance results in hyperinsulinemia, impaired fasting glucose and could even develop into diabetes mellitus in severe cases." (PMID 36750868, 2023).
Insulin resistance (continued). "Other types of studies focused on the insulin resistance, or hyperinsulinemia, that characterizes type 2 DM and speculated about the possibility of auditory damage directly induced by insulin level alterations." (PMID 36837470, 2023). "In addition, the mice in the M group exhibited a marked increase in fasting serum insulin (p < 0.001), as well as the homeostasis model assessment-insulin resistance (HOMA-IR) index (p < 0.001)." (PMID 37907988, 2023). "Mechanistically, our data evidence how environmentally promoted impairment of TH secretion and of their peripheral metabolism and signaling plays an important role in unbalancing the insulin signaling and originating the “pandemic insulin resistance and hyperglycemia”." (PMID 37298533, 2023). "Indeed, p27−/− NCD mice had elevated fasting serum insulin levels compared to the WT NCD mice, and WT HFD mice also tended to have increased insulin levels, suggesting the development of insulin resistance." (PMID 36768986, 2023). "The concept of selective insulin resistance was proposed by Brown and Goldstein about 15 years ago when they made a striking observation that systemic insulin resistance impairs the insulin-dependent lowering of plasma glucose, but the insulin-dependent lipogenesis in the liver remains increased." (PMID 37242206, 2023). "However, in mothers who develop GDM, maternal insulin production is insufficient to overcome insulin resistance and the mother develops hyperglycemia." (PMID 37650554, 2023). "Furthermore, alteration of microbiota profile as well microbial leakage causes pancreatic infection and inflammation that impairs the production of insulin and promotes insulin resistance leading to glucose intolerance and T2D." (PMID 37842639, 2023). "M1 macrophages produce pro-inflammatory cytokines, reactive oxygen species, and specific interferons, which can promote inflammatory responses and disrupt insulin signaling pathways, thereby contributing to the development or exacerbation of insulin resistance." (PMID 37511225, 2023). "Overall, these findings suggest a sex-differential reliance on intact renal tubular InsR signaling which may be translationally important in type 2 diabetes, obesity, or insulin resistance when renal insulin signaling is reduced." (PMID 37175762, 2023). "In addition to production of EETs and anti-inflammatory process, these genes are also involved in both insulin sensitivity in peripheral tissues and the capacity of the islets to respond to insulin resistance." (PMID 37370090, 2023). "There are a few molecular factors and pathways that have been identified as contributing to PI-induced insulin resistance, which includes the inhibition of glucose transporters, impaired insulin signaling, and altered lipogenic regulators and mitochondrial function." (PMID 37175645, 2023). "The TCM syndrome score, BMI, blood lipid (TG, LDL, HDL), glycometabolism indicators (fasting blood glucose, fasting insulin, glycosylated hemoglobin, and insulin resistance index (HOMA-IR)), and intestinal flora distribution were compared between the 2 groups before and after treatment." (PMID 38050318, 2023). "Interestingly, GH2 was also reported to increase pancreatic insulin secretion in human beta cells, although this role is less prominent than its role in promoting insulin resistance." (PMID 37049394, 2023). "AMPK is generally correlated with the increase in insulin sensitivity in the body and a decrease in insulin resistance as it is the inhibitor of acute proinflammatory responses and protects against obesity-induced insulin resistance." (PMID 37886939, 2023). "In conclusion, studies in animal models may imply that altered and decreased renal insulin signaling, mainly of the IR, may increase gluconeogenesis in the insulin resistance scenario, leading to other harmful effects." (PMID 37675359, 2023).
Insulin resistance (continued). "The accumulation of related metabolites and branched-chain ketone acids after elevated insulin levels may lead to further insulin resistance." (PMID 37781128, 2023). "The development of T2DM is mainly caused by a combination of two factors: the failure of insulin secretion by the pancreatic β-cells and the inability of insulin-sensitive tissues to respond to insulin (insulin resistance); therefore, the disease is indicated by a chronic increase in blood glucose." (PMID 37606429, 2023). "Similarly, increased insulin levels (mainly due to insulin resistance) and decreased adiponectin levels are correlated with increased risk of macrosomia and LGA newborns." (PMID 36520252, 2023). "In high-fat and STZ-induced diabetic mice, we found ZGJTSXF administration could improve fasting blood sugar, blood lipid, fasting blood insulin and insulin resistance." (PMID 36843604, 2023). "Furthermore, individuals with type 2 diabetes often exhibit insulin resistance, which leads to increased blood glucose levels due to inadequate insulin secretion." (PMID 37782659, 2023). "In summary, both the physiological actions of insulin and the development of insulin resistance are tissue specific and may facilitate a variety of adaptive survival responses in women with PCOS." (PMID 37109585, 2023). "Since long-chain AcCa might inhibit or disrupt the intracellular stage of insulin signaling, patients with T2D and insulin resistance often appeared AcCa perturbations." (PMID 36793054, 2023). "Furthermore, overnutrition, physical inactivity, obesity, smoking, and heredity factors reduce insulin sensitivity and increase insulin requirements for blood glucose regulation due to insulin resistance." (PMID 36839398, 2023). "Moreover, patients with higher LR Score values have higher T2DM risk, lower insulin sensitivity as determined by the ISI index, and higher hepatic insulin resistance, as determined by the HIRI index." (PMID 37537576, 2023). "Both TB1 and TB2 significantly enhanced PI3K and P-Akt/Akt ratios, suggesting that TB’s improvement of high-glucose and high-fat-induced insulin resistance may be achieved by activating insulin-related cell signaling." (PMID 37764646, 2023). "Moreover, it was shown that the peripheral target tissues of insulin are the sites wherein autophagy is triggered by ER stress-induced insulin resistance." (PMID 37876013, 2023). "Similarly, abnormal insulin sensitivity indicative of peripheral and whole-body insulin resistance has been noted." (PMID 37333522, 2023). "T2DM is characterized by insulin resistance, and decreased insulin secretion and decreased function of pancreatic beta cells may be the initiating factor in most cases." (PMID 38169604, 2023). "Owing to the fact that NF-kB could influence the insulin signaling system and play a role in producing insulin resistance, it is possible that inhibiting NF-kB activity could be a new approach to alleviate this condition." (PMID 37576807, 2023). "Dyslipidemia and ectopic fat in insulin-sensitive cells can induce insulin resistance via the increased accumulation of free fatty acids (FFAs), triglycerides (TGs), low-density lipoproteins (LDLs) and very-low-density lipoproteins (VLDLs), which, in turn, cause lipotoxicity." (PMID 37298274, 2023). "These raised cytokine levels impair insulin action and promote insulin resistance." (PMID 38140341, 2023). "Indeed, during this time, the non-stabilization group experienced deterioration of whole-body insulin sensitivity (Matsuda index) and hepatic insulin resistance (HOMA-IR), in contrast to the relative stability of these measures in the stabilization group." (PMID 37500612, 2023). "Furthermore, Oxidative stress, caused by an overproduction of ROS, leads to beta-cell dysfunction and apoptosis, hampering insulin production and secretion, and exacerbates insulin resistance, hindering insulin’s ability to promote glucose uptake by cells." (PMID 38137476, 2023).
Insulin resistance (continued). "Furthermore, childhood and adolescence are characterised by large hormonal changes, including rising insulin values and insulin resistance during puberty." (PMID 37420130, 2023). "LPL activity is increased by insulin and decreased by insulin resistance." (PMID 37009872, 2023). "In ARRDC4KO mice, hyperinsulinemic–euglycemic clamp experiments showed that hepatic glucose production during the insulin-stimulated state was significantly increased compared with WT mice, indicating hepatic insulin resistance–related insufficient suppression of glucose output in these mice." (PMID 37451484, 2023). "Several studies indicates that fasting insulin levels alone might accurately reflect insulin resistance." (PMID 38206747, 2023). "Although it is known that microglia express the IRs and respond to insulin treatment in vitro, it remained unknown whether they experience insulin resistance and whether that impacts their phagocytic activity." (PMID 37934726, 2023). "This insulin-sensitizing effect of estrogen is related to its influence on adipose tissue distribution: estrogen prevents the accumulation of visceral abdominal fat in female mice and protects them from developing insulin resistance." (PMID 36979669, 2023). "Furthermore, increased levels of ROS resulting from hyperglycemia disturbs the insulin signaling cascades and encourages the development of insulin resistance." (PMID 36677055, 2023). "However, Asians, including the Chinese and Japanese, tend to have lower insulin levels and mild insulin resistance at T2D onset." (PMID 36872318, 2023). "Insulin dysregulation can be manifested in basal hyperinsulinemia, which is abnormal hyperinsulinemia in response to carbohydrate administration (oral or intravenous) or insulin resistance." (PMID 37628596, 2023). "In relation to the metabolic syndrome, other adipokines also act, such as resistin, which facilitates insulin resistance, and adiponectin, which regulates insulin sensitivity and maintains anti-inflammatory effects associated with the modulation of endothelial damage." (PMID 37238961, 2023). "We then blocked CNS insulin action as a model of CNS insulin resistance by injecting S961 ICV." (PMID 37076875, 2023). "Body weight with increased adiposity is mechanistically linked to both the development and the progression of type 2 diabetes, typified by resistance to insulin action (insulin resistance) and an inadequate compensatory insulin secretory response by pancreatic beta cells." (PMID 36786838, 2023). "The hypothesis was that children in the Texas Sprouts intervention compared with control will have improvements in glucose control and lipids and reductions in insulin and insulin resistance." (PMID 36626172, 2023). "We also found increased AKT phosphorylation upon HIBCH knockdown, suggesting that HIBCH may contribute to hepatic insulin resistance, in line with a reduced insulin response upon 3-HIB exposure of myocytes and adipocytes." (PMID 37084480, 2023). "The results showed an improvement in insulin resistance and an increase in the secretion of insulin (40%) in INS-1 cells, a reduction in glucose levels in obese mice (20%), as well as a decreased in body weight (25%) the supplemented obese mice between baseline and day 30 of treatment." (PMID 37432178, 2023). "Plasma glucose elevations could arise from either insulin resistance or impaired pancreatic insulin secretion, with skeletal muscle being the major tissue involved in insulin stimulated peripheral glucose uptake, and thus also insulin resistance." (PMID 37333553, 2023). "Importantly, high concentrations of plasma insulin are considered a biomarker of hepatic insulin resistance (IR)." (PMID 37513467, 2023). "Brain insulin resistance refers to reaction failure of brain cells to insulin." (PMID 37009459, 2023). "Besides, the obese DM group had significantly higher levels of insulin and insulin resistance in comparison with other groups." (PMID 37208686, 2023).
Insulin resistance (continued). "Curcumin has increased insulin sensitivity substantially and reduced insulin resistance." (PMID 37346347, 2023). "A long hyperglycemic environment in the body and disturbed lipid metabolism caused by chronically elevated FFA reduced function and activity of beta cells, sharply decreases insulin secretion and aggravates persistent insulin resistance, leading to the onset of ketosis." (PMID 37829685, 2023). "Similarly, MGO-injected mice have developed systemic insulin resistance resulting from the impairment of the insulin-triggered signaling pathway, as observed in the murine aortas and endothelial cells." (PMID 38067472, 2023). "Rodent models also suggest that, independent of insulin resistance, androgen excess causes chronic androgen receptor activation in beta cells, promoting insulin hypersecretion, and secondary beta cell failure." (PMID 36484476, 2023). "Insulin resistance can increase energy supply for lipid oxidation, promote glucose phosphorylation in muscle cells, and transform blood sugar to myosin to make glucose more stable, thereby maintaining the balance between glucose and insulin secretion." (PMID 36761189, 2023). "Parameters of insulin resistance such as fasting insulin (GW < 20: 12.7 ± 8.5 μIU/mL, GW 24–28: 18.3 ± 17.5 μIU/mL, Postpartum: 10.9 ± 6.4 μIU/mL) and HOMA2-IR (GW < 20: 1.6 (± 1.05), GW 24–28: 2.12 (± 1.63), Postpartum 1.41 (± 0.83)) increased over the course of pregnancy and decreased postpartum." (PMID 37518503, 2023). "Since every pregnancy is characterized by a certain degree of insulin resistance, we have also noted a negative association of insulin levels and insulin resistance markers with low-branched glycans and a positive one with high-branched glycans." (PMID 37079606, 2023). "Some studies suggest that ChREBPβ may play a more important role in the regulation of insulin sensitivity than ChREBPα, and that dysregulation of ChREBPβ may contribute to the development of insulin resistance and T2DM." (PMID 37240157, 2023). "However, 30-wk-old Slc12a2βKO mice fed a chow diet showed increased fed and 6 h-fasted plasma insulin in the context of normal blood glucose, glucose intolerance, and insulin resistance." (PMID 37819196, 2023). "However, insulin resistance disrupts INSR-mediated tyrosine kinase activities resulting in insufficient activation of the PI3K/Akt signaling cascade upon insulin stimulation." (PMID 37715850, 2023). "The proinsulin/insulin ratio can be the predictor of insulin resistance and β-cell dysfunction." (PMID 37237539, 2023). "Insulin resistance (IR), which is characterized by reduced insulin sensitivity, could lead to an insufficient physiological response to a normal amount of insulin." (PMID 37602260, 2023). "Discrepant findings may be due to varied proportion of insulin resistance, and/or impaired insulin secretion (due to impaired incretin production or incretin resistance) in women with different GDM phenotypes." (PMID 36717953, 2023). "Thus, further utilization of simple surrogate indexes for insulin resistance, such as quantitative insulin sensitivity check index, and insulin secretion by the HOMA‐β cell index will be needed to fully characterize insulin sensitivity and secretion." (PMID 37170065, 2023). "Thus, the progressive improvement in insulin resistance can counterbalance the inhibitory effect on insulin secretion, which appears mainly at the initiation of treatment, and in the long term, glucose tolerance can be improved." (PMID 37628857, 2023). "Moreover, decreased estrogen levels can cause an increase in pro-inflammatory cytokine levels and decrease hepatic insulin clearance, allowing the development of diet-induced insulin resistance, thus promoting the formation of MAFLD." (PMID 37822594, 2023). "However, it is unusual for patients with a mild infection to present with severe hyperglycemia and insulin resistance requiring intravenous insulin therapy." (PMID 37456416, 2023).